OR8J1 (olfactory receptor family 8 subfamily J member 1)
Description:
Odorant receptor.
Synonyms: OR11-183
Tractability: Antibody: UniProt places it where antibodies can reach, with medium confidence; UniProt predicts a signal peptide or a membrane-spanning region; its Gene Ontology location is reachable by antibodies, with medium confidence.
Gene: Protein-coding gene on chromosome 11 (56,354,291 to 56,361,511, forward strand). Ensembl gene ENSG00000172487.
Subcellular location: Cell membrane
Pathways (Reactome):
Sensory Perception: Expression and translocation of olfactory receptors
Gene Ontology:
Molecular function: olfactory receptor activity; G protein-coupled receptor activity
Biological process: G protein-coupled receptor signaling pathway; sensory perception of smell; detection of chemical stimulus involved in sensory perception of smell
Cellular component: plasma membrane; membrane
Genetic constraint (gnomAD): Missense variants: 336 observed, 302.93 expected, observed/expected ratio (o/e) 1.11, 90% interval 1.01 to 1.21. Synonymous variants: 126 observed, 116.7 expected, observed/expected ratio (o/e) 1.08, 90% interval 0.93 to 1.25.
Homologues: Orthologues: chimpanzee OR8J1 (97% identical), macaque OR8J1 (93% identical), mouse Or8j3 (84% identical), rat Or8j3 (82% identical), dog OR8J3 (80% identical). Paralogues in human: OR8J3 (89% identical), OR8J2 (77% identical), OR8K3 (58% identical), OR8U1 (56% identical), OR8U3 (56% identical), OR8K5 (56% identical), OR8K1 (53% identical), OR5M11 (51% identical), OR5I1 (51% identical), OR5D18 (50% identical), OR8D1 (50% identical), OR8B12 (50% identical), and 84 more.
Diseases named in the same sentence as OR8J1 in open-access papers:
OR8J1 is named in the same sentence as 1 disease in open-access papers, as found by Europe PMC text mining. Sharing a sentence is not in itself a finding about the gene and the disease.
OR8J1 shares sentences with these, for which no sentence is quoted: gastric cancer (1 paper).